NR1H2 (nuclear receptor subfamily 1 group H member 2)
Diseases named in the same sentence as NR1H2 in open-access papers (continued):
Sharing a sentence is not in itself a finding about the gene and the disease.
depression (1 paper, 2024). "From a new perspective, the study explores the molecular interactions between stress-induced damage and cholesterol metabolism, elucidating the roles of NR3C1/NRIP1/NR1H2 in the mechanisms underlying depression-like behavior induced by short-term restraint stress." (PMID 39125645, 2024).
Hypercholesterolemia (1 paper, 2020). An increased concentration of cholesterol in the blood. "In our study, hypermethylation of promoters of key genes regulating cholesterol metabolism such as PCSK9, LRP1, ABCG1, ANGPTL4, SREBF1 and NR1H2, were found in obese patients with hypercholesterolemia." (PMID 33028190, 2020).
liver cancer (1 paper, 2016). An epithelial or non-epithelial malignant neoplasm that arises from the liver. "Although having been reported to regulate cholesterol homeostasis and tumorigenesis of liver cancer, the role of NR1H2 Q175 insertion in BRCA has not been well characterized." (PMID 27356755, 2016).
lymph node metastasis (1 paper, 2020). "The combined expression of sterol regulatory element-binding protein 2 (SREBP2) together with HMGCR, NR1H3, and NR1H2 genes was associated with poor CRC clinical outcome independent of lymph node metastasis, distant metastasis, and advanced stage." (PMID 33194695, 2020). "Moreover, one study reports that NR1H3 and NR1H2 belong to a transcription signature associated with poor CRC clinical outcome independent of lymph node metastasis, distant metastasis, and advanced stage." (PMID 33194695, 2020).
prediabetes (1 paper, 2024). "Our data showed that, in addition to coexpressed ABCG1, ABCA1, and MYLIP, expression of NR1H2 (encoding LXRβ) itself was also inversely associated with incident prediabetes/T2D, suggesting, for the first time to our knowledge, that dysregulated LAAMP is a major risk factor for T2D." (PMID 38747290, 2024).
steatosis (1 paper, 2023). Increased lipid within the cytoplasm of cells. "In addition, this treatment seemed to play the role of metabolic protection being capable to restore the normal level of genes expression upregulated after steatosis treatment, between them RXRA, NR1H2, CEBPB, ADIPOR2, and CYP2E1." (PMID 36770927, 2023).
ventricular dilatation (1 paper, 2022). "Heart weight and ventricular dilatation were significantly alleviated by Nr1H2 overexpression in HFD-STZ-treated mice." (PMID 36438502, 2022).
cancer (23 papers, 2010 to 2025). A tumor composed of atypical neoplastic, often pleomorphic cells that invade other tissues. "First, master regulators of cell cholesterol homeostasis are already deregulated in primary cancer, with a decreased expression of NR1H2, coding for LXRβ, which is associated with the management of excess cholesterol." (PMID 38893271, 2024). "Therefore, this suggests that NR1H2 can be a potential therapeutic target for the treatment of many types of cancers." (PMID 29065888, 2017). "In addition to their role in lipid metabolism, the nuclear receptors Liver X Receptor α (LXRα or NR1H3) and β (or NR1H2) have been shown to control cancer cell proliferation and to a lesser extent, cancer cell death, in vitro and in vivo." (PMID 26450852, 2015). "Lastly, “Signal transduction” includes nuclear receptor signaling, including NR1H2 and NR1H3-mediated signaling, ErbB cancer signaling and p75 NTR death signaling; note that NOTCH signaling was reported previously." (PMID 36437990, 2022). "Moreover, our network analysis indicated alterations in MAPK/ERK and Jun-N-terminal kinase pathways and the potential important role of PAX3, VCAN, ARRB2, NR1H2, and ITGA5 that may provide insights into mechanisms involved in longevity and regeneration that are distinct from cancer." (PMID 22477361, 2013).
tumor (11 papers, 2016 to 2026). "NR1H2 and NR1H3 are hepatic nuclear receptors that have been associated with lipogenesis and tumor cell growth." (PMID 41557483, 2026). "GADD45B-high tumor cells showed strong associations with transcription factors such as ELK1, PAX5, SMAD3, BACH1, and NR1H2." (PMID 37608794, 2023). "We then set out to test if expression of a wider and unbiased set of LXR target genes correlated with NR1H3/LXRA or NR1H2/LXRB expression in ER-positive or ER-negative tumours." (PMID 31683867, 2019). "Recently, a scRNA-seq study of six metastatic omental tumors that derived from primary HGSOCs unraveled the genetic signatures of immune cell subsets within the tumor microenvironment and identified NR1H2+ IRF8+ and CD274+ macrophage clusters, which were suggested with an anti-tumor response." (PMID 35935940, 2022). "The results from HPA database showed that the immunohistochemical staining intensity of SDHB, GZMA, BTK, EEF2K, and NR1H2 in glandular cells of normal tissues was stronger than tumor cells, demonstrating that these genes were significantly expressed in normal colon tissues than in tumor tissues." (PMID 35912258, 2022). "To clarify the correlation between 7 PRGs (BTK, CASP5, EEF2K, GZMA, NR1H2, RIPK3, and SDHB) derived from LASSO Cox regression analysis and immune infiltration in COAD, we applied Tumor Immune Estimation Resource (TIMER) database on these genes." (PMID 35912258, 2022). "NR1H2/NR1H3 ligands secreted by tumor cells inhibit CCR7 expression on maturing dendritic cells, impairing immune-surveillance and favoring tumor growth." (PMID 26894976, 2016). "Both ABCA1 and APOE were assessed for correlation with NR1H2/LXRB and whilst APOE weakly correlated with NR1H2/LXRB in ER-positive tumours (R = 0.25) it was not correlated in ER-negative tumours; ABCA1 was not correlated with NR1H2/LXRB in either tumour type." (PMID 31683867, 2019).
metabolic disease (1 paper, 2014). A congenital disorder (due to inherited enzyme abnormality) or acquired (due to failure of a metabolically important organ) disorder resulting from an abnormal metabolic process. "Most studies have focused on the NR1H2 gene and most studies have suggested that the LXR gene polymorphisms are associated with susceptibility and outcome of metabolic diseases." (PMID 24886807, 2014).
NR1H2 also shares sentences with these, for which no sentence is quoted: skin cancer (9 papers); xeroderma pigmentosum (9); bladder cancer (3); colon cancer (3); fatty liver disease (3); gastric cancer (2); Hepatic steatosis (2); prostate carcinoma (2); tuberculosis (2); arterial hypertension (1); cervical cancer (1); cholesterol metabolism disorders (1); Cockayne syndrome (1); cognitive decline (1); colorectal adenocarcinoma (1); congenital heart defects (1); coronary artery disease (1); Cortical Dysplasia (1); gallbladder cancer (1); gallstones (1); glucose metabolism disorders (1); GNE myopathy (1); head and neck tumors (1); hypertriglyceridemia (1); infection (1); infertile (1); laryngeal carcinoma (1); leukemia (1); liver disease (1); metabolic syndrome (1).
A further 8 diseases each share a sentence with NR1H2 in 1 paper.